INS (insulin)
Diseases named in the same sentence as INS in open-access papers (continued):
Sharing a sentence is not in itself a finding about the gene and the disease.
Obesity (continued). "Herein, to study if OXT treatment has a beneficial effect on beta cells, we used streptozotocin (STZ)-induced diabetic mouse model which suffers from beta cell damage and insulin secretion impairment which resemble T1D and late-stage T2D, but does not have overeating or obesity." (PMID 23700406, 2013). "It is not known whether the bone is relatively spared in obesity despite the cellular resistance to insulin in critical tissues such as fat, liver and muscles." (PMID 25258705, 2013). "However, the relationship between gut microbiota and insulin action in human obesity has never been established." (PMID 22711164, 2013). "Moreover, CGA, unlike thiazolidinedione (TZD) or insulin, does not induce obesity or other side effects." (PMID 24062792, 2013). "It seems that reduction in ghrelin in obesity is independent of the influence on insulin." (PMID 24354802, 2013). "Together, the altered hormonal and inflammatory milieu of obesity may contribute significantly to cancer growth and progression via promoting mitogenesis (e.g., leptin, IGF-1, insulin), angiogenesis (e.g., VEGF, IL6, IL8), and invasion (e.g., leptin, IL6, PAI-1, CCL5, CCL2)." (PMID 23573093, 2013). "Formerly overweight (obesity-prone) AA women were more insulin sensitive than never overweight AA women, a quality that may predispose to adiposity, particularly when combined with a high GL diet." (PMID 23298367, 2013). "Thus, Trim72 could be a useful therapeutic target in obesity, IR, and T2DM because insulin sensitivity and glucose uptake is highly increased in the enhanced skeletal muscle." (PMID 23326526, 2013). "Importantly, these HFD-induced effects occurred without significant body weight gain, obesity, or major effects on glucose and insulin levels, or E and P levels." (PMID 24156623, 2013). "Pediatric prediabetic states, for instance, may present with significant inflammatory alterations; in pre-type 2 diabetes, the enormous increase in circulating insulin may act by itself as a major inflammatory modulator, independent of obesity status." (PMID 23093953, 2012). "Experiments in animal models also support this concept since, for instance, overexpressing adiponectin in adipose tissue leads to a marked hypercellular obesity without adipose cell enlargement and the animals are at least as insulin sensitive as the lean wildtype mice." (PMID 22992414, 2012). "However, it is important to point out that even in the age-related obesity model, combined deletion of both p/CIP and SRC-1 resulted in much more drastic phenotypes in terms of obesity and insulin responses, illustrating again redundant roles of p/CIP and SRC-1 in this model." (PMID 22859932, 2012). "The lack of LPL in beta cells of ob/ob mice could be due to the lack of leptin per se, or could be a consequence of obesity and/or the high levels of glucose, fatty acids and insulin in the blood." (PMID 23186339, 2012). "Our current study demonstrated for the first time that α7-nAChR agonist had insulin sensitizing action not only in normal mice, but also in insulin resistant mice, i.e., AMPKα2−/− mice, a model with no sign of inflammation and obesity, which is different from db/db mice." (PMID 23251458, 2012). "An excessive insulin signalling produced by an overstimulation of β-cells by BPA exposure may produce dyslipidemia resulting from effects in the liver and adipose tissue, and obesity and glucose intolerance." (PMID 22347437, 2012). "In humans, evidence exists for the ability of insulin to promote inflammation during acute, experimentally-induced hyperinsulinemia, independent of obesity, increasing inflammatory cytokine concentrations in subcutaneous adipose tissue interstitial fluid as well as circulating IL-6 concentrations." (PMID 26486919, 2012).
Obesity (continued). "Studies have shown that a reduction of 5–10% body weight is sufficient to significantly improve many of the known obesity-related blood biochemistry parameters, including hyperlipidemia, insulin and leptin resistance, and increased circulating nonesterified fatty acids (NEFA)." (PMID 21904565, 2012). "On the other hand, insulin-sensitizing effects of ghrelin did not occur in gastrocnemius muscle in lean rodents and this finding is consistent with the current observations in diet-induced obesity." (PMID 22039445, 2011). "Moreover, in obesity, IGFBP-2 was shown recently to reflect long-term insulin sensitivity." (PMID 22242132, 2011). "D2KO mice are also less responsive to insulin, independent of diet-induced obesity." (PMID 21698184, 2011). "However, our data suggest that the decreased spontaneous 24-hour GH release observed in obesity seems related to the concomitant hyperinsulinaemia and insulin sensitivity rather than elevated FFA levels." (PMID 21826141, 2011). "Our data strongly suggests that the early evolution of obesity-induced elevation of nocturnal FFA may directly modulate GSIS in the pancreas and/or indirectly reduce hepatic insulin clearance, either mechanism serving as a potential hyperinsulinemic compensatory signal." (PMID 21479217, 2011). "To test this hypothesis, we employed the HFD-induced obesity and T2DM model and treated orally with GABA to test whether activation of GABA receptors could prevent the HFD-induced obesity and T2DM, and improve glucose tolerance and insulin sensitivity after the onset of T2DM." (PMID 21966503, 2011). "In murine models of obesity and insulin resistance, incorporation of LC n-3 PUFA into cell membrane phospholipids increases membrane fluidity and expression, affinity, and number of insulin receptors as well as GLUT-4 protein level in adipocytes, thereby improving insulin sensitivity." (PMID 21197079, 2011). "During the development of obesity and T2DM, adipocytes can produce adipokines and other factors, which recruit the infiltration of macrophages and other immunocompetent cells into the adipose tissues and affect insulin sensitivity in other organs, leading to low grade inflammation." (PMID 21966503, 2011). "Whether astrocyte numbers are higher in persons with higher insulin levels (e.g. in obesity) has not been studied." (PMID 21738722, 2011). "With obesity and T2DM reaching epidemic proportions, it is important to assess the role of excessive FFA supply regarding endothelial injury and inflammation because both conditions are characterized by increased rates of lipolysis and plasma FFA due to adipose tissue insulin resistance." (PMID 20158910, 2010). "In contrast to those studies exhibiting detrimental effects of amino acids on NAFLD and insulin signaling, several clinical trials and animal experiments have demonstrated that KAA supplementation can have beneficial effects on insulin sensitivity and/or obesity." (PMID 20706589, 2010). "Diastolic blood pressure was also significantly higher in AFLD than in NAFLD, which could also be due to alcohol use independent of obesity and insulin." (PMID 20459722, 2010). "IRS-1, principal substrate for insulin and insulin like growth factor (IGF-1) receptors is involved in glucose clearance and is an attractive candidate gene to harbor genetic variation that might influence insulin resistance and obesity." (PMID 20300294, 2008). "These discrepancies should be considered to be indicative of body fat content, and adjustments required for BMI or waist circumferences to define obesity do not entirely account for possible differences in inherent insulin resistance in the South Asian population." (PMID 17726542, 2007). "The increased level of PPARα measured in the liver of KOmice could be suspect of exerting to negative effect on insulin action and obesity." (PMID 17389764, 2007).
Obesity (continued). "In addition, twin-pair normalization also resulted in clearer negative correlations of HDL cholesterol with obesity and with insulin sensitivity than correlations at individual level." (PMID 17299598, 2007). "We also demonstrated that rats with EV-induced PCO do not have reduced insulin sensitivity and do not develop obesity or hyperandrogenism, which might be later signs of sympathetic hyperactivity." (PMID 16146570, 2005). "Thus, rats with EV-induced PCO develop hypertension and increased sympathetic and HPA-axis activity without reduced insulin sensitivity, obesity, or hyperandrogenism." (PMID 16146570, 2005). "Importantly, these findings indicate a lack of response in individuals with prediabetes, aligning with previous observations where a 4-week oral butyrate supplementation altered insulin sensitivity and metabolism in lean individuals but not in those with obesity and IR." (PMID 40587382, 2026). "It was subsequently recognized that insulin-resistant states are characterized by resistance to the metabolic actions of insulin rather than true insulin insufficiency, and may coexist with either obesity and/or other features of the metabolic syndrome or acanthosis nigricans." (PMID 40141412, 2025). "Among overweight individuals—even those not meeting obesity criteria—multidomain lifestyle interventions targeting structured dietary control, increased physical activity, and circadian rhythm optimization are warranted to enhance insulin sensitivity and mitigate disease progression." (PMID 40365140, 2025). "CD248, which has been recently linked with insulin metabolism, NAD(P)H quinone dehydrogenase 1 (NQO1) and tenomodulin (TNMD) were downregulated following LIWL, and their expression was also reduced in SAT of individuals with or without obesity of the LATC and OA cohort." (PMID 40229590, 2025). "Moreover, we find in this study that sevelamer administration leads to a significant improvement in peripheral insulin sensitivity in non-diabetic subjects with obesity, as measured using insulin clamping, the gold standard for quantitating insulin sensitivity." (PMID 40666326, 2025). "The precise mechanisms connecting excess weight or obesity to liver cancer are not entirely clear, but it’s believed that changes in gut microbial metabolites, insulin resistance, and the generation of cytokines that may promote tumors, along with liver inflammation, play significant roles." (PMID 40168281, 2025). "The recent accumulation of data establishing a link between insulin signaling components, metabolic dysfunction, and the regulation of gene rhythmicity prompted us to investigate whether hepatocyte p110α contributes to the remodeling of gene expression during HFD-induced obesity." (PMID 40228209, 2025). "In addition, we saw positive correlations between the GLP‐1/chromogranin A ratio and the determinants of defective glucose homeostasis, such as HbA1C and glucose AUC of the meal test among patients with obesity, but a negative correlation with blood glucose and insulin levels in the controls." (PMID 40790227, 2025). "KEGG pathway enrichment of DALs indicated that the anti-obesity mechanism of WMSZY may involve lipid and atherosclerosis pathways, cholesterol metabolism, regulation of adipocyte lipolysis, fat digestion and absorption, insulin resistance, and glycerolipid metabolism." (PMID 41194880, 2025). "Obesity phenotypes, including MUHO and metabolically healthy obesity (MHO), were classified based on the Joint Interim Statement criteria for metabolic syndrome, which rely on clinical and biochemical cardiometabolic risk markers rather than insulin resistance or inflammatory profiles." (PMID 40699839, 2025). "Additionally, RSG can improve insulin sensitivity by specifically targeting the outer mitochondrial membrane protein MitoNEET, which, in turn, induces WAT expansion, mitochondrial activity, and adiponectin secretion, thus reducing obesity-induced inflammation and oxidative stress." (PMID 39339665, 2024).
Obesity (continued). "Partial substitution of glucose with galactose in high-fat diet (HFD)-challenged female mice reduces BW, obesity, homeostatic model assessment of IR (HOMA-IR), and induces genes involved in insulin signaling in white adipose tissue depots, which could explain improved insulin sensitivity." (PMID 39272602, 2024). "Moreover, obesity-induced visceral fat accommodation leads to induced liver lipoprotein production that affects triglyceride-rich VLDL levels, low-density lipoprotein (LDL) and total cholesterol levels and results in increased necrosis of blood vessels and induced insulin resistance." (PMID 39598313, 2024). "Indeed, recently it has been proven that SCD1 deficient mice (Scd1−/−) exhibit enhanced energy expenditure, improved insulin sensitivity of skeletal muscle, and high resistance to diet-induced weight gain, which collectively highlight the close link between SCD1 overactivity and obesity occurrence." (PMID 38919749, 2024). "However, disease states (e.g., obesity, Cushing’s syndrome, type 1 diabetes [T1D] and anorexia nervosa) and some commonly used drugs [e.g., glucocorticoids and glucagon-like peptide 1 receptor agonists (GLP-1RAs)] that impact pancreatic β-cell insulin secretion can also alter the GH/IGF-I axis." (PMID 39665021, 2024). "LCN2 participated in obesity and its metabolic complications such as T2DM, and cardiovascular diseases, which may relate to the activation of LCN2 signaling (such as TNF-α/NLRP3/LCN2) inducing mitochondrial dysfunction, oxidative stress, insulin resistance, and macrophage activation in adipocytes." (PMID 39609876, 2024). "Furthermore, butyrate generated by butyrate-producing bacteria, such as Feacalibacterium prausnitzii, may also exert anti-obesity effects by stimulating GLP-1 secretion from colon L cells via fatty acid receptor (FFAR2)-mediated signaling and mitigating insulin resistance." (PMID 39545049, 2024). "Asian Indian populations could be insulin resistant even without overt obesity." (PMID 38923743, 2024). "Due to the potent function of BAT and beige adipose tissue on fat burning and energy expenditure, targeting these thermogenic adipose tissues could be a promising strategy to combat obesity and thus obesity-related diabetes, independent of insulin and glucose levels." (PMID 37435495, 2023). "Also, when treated cells with SERPINE1 and insulin, the activation of AKT further induced SERPINE1 expression in a positive-feedback manner, indicating that SERPINE1 might modulate cancer aggressiveness under the control of AKT signaling in obesity." (PMID 36681663, 2023). "Apart from the glucose clamp test, most of these tests are not accurate in assessing the change in insulin sensitivity, and the studies that used the glucose clamp test had a small sample size and a lot of variability among participants in terms of diabetic status, and degree of obesity." (PMID 36200436, 2023). "The data suggest elevated insulin signaling (hyperinsulinemia) promotes weight gain and an increase in fat mass with a concomitant increase in circulating leptin levels inducing central insulin and leptin resistance, subsequently leading to obesity, hyperphagia and lack of satiety." (PMID 37546289, 2023). "Furthermore, certain participant characteristics, such as obesity and insulin secretion levels, were not available, which may confound the association." (PMID 38047115, 2023). "Preventing or reversing elevated insulin levels in PWS with pharmacological agents and/or through diet restrictions such as a combined low carbohydrate, low glycemic‐load diet may be a viable therapeutic strategy in combating obesity in children with PWS and others with early childhood obesity." (PMID 37546289, 2023).
Obesity (continued). "Additionally, our data show a lack of response in individuals with prediabetes, which is consistent with the observation that a 4-week oral administration of butyrate altered metabolism and insulin sensitivity in lean individuals but not in individuals with obesity and IR." (PMID 37581871, 2023). "However, under chronic nutrient overload as in obesity and metabolic syndrome, β‐cells secrete insulin in response to fatty acids, even at low glucose concentrations, contributing to elevated insulin secretion at nonstimulatory conditions that is characteristic of the obese prediabetic state." (PMID 36917141, 2023). "Indeed, PTP1B-knockout mice exhibited a phenotype ascribable to both enhanced leptin and insulin signaling, characterized by improved sensitivity of target tissues to insulin and resistance to diet-induced obesity, without any alterations in growth or viability." (PMID 37298571, 2023). "As IPFD may accumulate because of a paracrine action of pancreatic local insulin secretion, postprandial hyperglycemia and local hyperinsulinemia may explain the association between fast eating and IPFD, independent of the effects of obesity and IHLA." (PMID 37576958, 2023). "Taken together, these data show that obesity, especially in the visceral white adipose tissue, shapes a condition in which GC signaling in macrophages affects ATM polarization and could feasibly modulate adipose tissue function and whole-body insulin sensitivity." (PMID 37080971, 2023). "Furthermore, obesity promotes an imbalance between glucagon-like peptide-1 (GLP-1) and glucagon-like peptide-2 (GLP-2), impairing the incretin axis, which contributes to the appearance of insulin resistance; therefore, this whole process becomes involved in a vicious cycle." (PMID 37298013, 2023). "Although these data suggest the existence of an endocrine circuit between FABP4 and insulin, which could coordinate the response of β-cells to obesity, there is a lack of further studies confirming the role of this endocrine loop in β-cell compensatory insulin hypersecretion during obesity." (PMID 35628332, 2022). "Interestingly, the positive effects of myo-inositol occur in the presence or absence of hyperandrogenic and hyperinsulinemic in vitro conditions, suggesting that the action of insulin-sensitizing molecules is effective in an obesity environment independent of PCOS." (PMID 35409282, 2022). "However, there is a lack of studies comparing insulin action after the two interventions in individuals with obesity-induced T2D by combining gold standard 2-step hyperinsulinemic glucose clamps with isotope dilution methodology and including a healthy control group." (PMID 36589629, 2022). "Additionally, the lack of insulin secretion after fructose ingestion also reduces leptin secretion by adipocytes, which may increase food intake, leading to weight gain and obesity." (PMID 35380611, 2022). "Furthermore, serum levels of CTRP9 protein are positively correlated with BMI, waist circumference, fasting insulin levels, decreased hemoglobin levels, and HOMA-IR, suggesting that the correlation between CTRP9 and non-alcoholic fatty liver is most likely due to the effect of CTRP9 on obesity." (PMID 35370782, 2022). "Therefore, a judicious exogenous insulin therapy provided in a near-physiological dose may prevent obesity in affected individuals by inducing satiety without promoting exaggerated fat deposition." (PMID 35963866, 2022). "This is supported by our recent cross-sectional study in Black South African women with obesity in which we showed that higher VAT levels, and not pancreatic or hepatic fat, were associated with lower first-phase insulin secretion and higher hepatic insulin clearance." (PMID 36166072, 2022). "In HFD-induced obesity in mice, oral administration of A. muciniphila could reverse metabolic syndrome including fat-mass gain, metabolic endotoxemia, adipose tissue inflammation, and insulin resistance without influencing food intake." (PMID 35812447, 2022).